IRF3 (interferon regulatory factor 3)
Diseases named in the same sentence as IRF3 in open-access papers (continued):
Sharing a sentence is not in itself a finding about the gene and the disease.
osteosarcoma (7 papers, 2013 to 2026). A usually aggressive malignant bone-forming mesenchymal neoplasm, predominantly affecting adolescents and young adults. "Having established that the SGLT2 inhibitor activates the STING/IRF3/IFN-β pathway in osteosarcoma cells, we investigated the potential synergistic effects of the STING pathway agonist 2’3’-cGAMP and the SGLT2 inhibitor in osteosarcoma." (PMID 35662245, 2022). "Here, we explored the ability of the SGLT2 inhibitor to activate the STING/IRF3 pathway in osteosarcoma cells." (PMID 35662245, 2022). "In contrast, our study indicated that the overexpression of TRIM21 resulted in an increased degradation of SGLT2, which induced the expression of STING and the activation of the IRF3/IFN-β pathway in osteosarcoma." (PMID 35662245, 2022). "Consistent with our model that LUBAC is not a negative regulator of MAVS signaling, tetracycline-inducible knockdown of HOIP in the human osteosarcoma cell line U2OS modestly inhibited the activation of IRF3 and induction of IFNβ by VSV." (PMID 23951545, 2013). "Furthermore, the combined treatment with SGLT2 inhibitor and STING agonist 2’3’-cGAMP exerted synergistic antitumor effects in osteosarcoma due to the activation of the STING/IRF3/IFN-β pathway via different mechanisms." (PMID 35662245, 2022). "CANA activated the STING/IRF3/IFN-β pathway in K7M2 tumor-bearing mice and osteosarcoma cells by impeding AKT phosphorylation levels, thereby synergistically inhibiting tumor growth when combined with 2′3′-cGAMP." (PMID 38595915, 2024). "First of all, we verified that 2’3’-cGAMP also increased the expression level of p-STING, p-IRF3, p-TBK1 and IFN-β in osteosarcoma cells." (PMID 35662245, 2022). "In our study, we found that the SGLT2 inhibitor significantly inhibited osteosarcoma tumor growth in vivo, which could be attributed to the up-regulation of STING expression and activation of the IRF3/IFN-β pathway induced by the SGLT2 inhibitor." (PMID 35662245, 2022). "Finally, STING silencing significantly inhibited the up-regulation of p-IRF3 and IFN-β expression induced by SGLT2 inhibitor treatment in osteosarcoma cells, which suggesting that the SGLT2 inhibitor activated the STING/IRF3/IFN-β pathway in osteosarcoma cells." (PMID 35662245, 2022). "Furthermore, our results showed that the SGLT2 inhibitor significantly inhibited osteosarcoma tumor growth and induced infiltration of immune cells in vivo by upregulating STING expression and activating the IRF3/IFN-β pathway, which could attribute to the suppression of AKT phosphorylation." (PMID 35662245, 2022).
Rotavirus infection (7 papers, 2018 to 2023). Infection with any of the rotaviruses. "Vitamin D alleviated rotavirus infection through the TBK1/IRF3 signaling pathway via directly targeting TBK1." (PMID 35462942, 2022). "In pre-infection experiments, cells were treated with C. sorokiniana followed by rotavirus infection, showing that IFN-α, IRF-3, and RIG-I relative expression was significantly (p < 0.05) upregulated, as compared with that in rotavirus-infected cells without treatment." (PMID 37317211, 2023).
acute pyelonephritis (6 papers, 2010 to 2025). "The results further demonstrate the potent effects of IL-1RA treatment against acute pyelonephritis in susceptible Irf3−/− mice." (PMID 38251349, 2023). "The present study extends the therapeutic window to include acute pyelonephritis, in this case in Irf3−/− mice, which are susceptible to infection due to a transcription factor deficiency that impairs the type I IFN response and the antibacterial defense." (PMID 38251349, 2023). "Genetic factors involved in host susceptibility to acute pyelonephritis have been described including polymorphisms that reduce expression of the interferon regulatory factor 3 (IRF3) or CXCR1 coding for the IL-8 receptor." (PMID 31284699, 2019). "In patients with UTI, polymorphisms affecting the IRF3 promoter have been detected, and the genotype associated with low promoter function is associated with acute pyelonephritis." (PMID 22140570, 2011). "In acute pyelonephritis, IRF3 is required for mucosal innate immunity and protects the kidney from uropathogenic E. coli, whereas IRF7 agonism triggers a hyperinflammatory response and increases kidney injury." (PMID 41212050, 2025). "Gene deletions result in an exaggerated, dysfunctional inflammatory response and in aggravated acute pyelonephritis in Irf3-/- mice." (PMID 22140570, 2011). "Mice lacking Irf3, in contrast, develop severe acute pyelonephritis with urosepsis and renal damage." (PMID 22140570, 2011).
alcoholic liver diseases (6 papers, 2017 to 2025). A disorder caused by damage to the liver parenchyma due to alcohol consumption. "Mice that were simultaneously genetically engineered to have lower levels of cGAS and IRF3 expression were less susceptible to alcoholic liver disease." (PMID 35536585, 2022). "Research examining the role of STING in ER stress during the initial stages of alcoholic liver disease has also provided evidence showcasing the presence of IRF3 within mitochondrial fractions at basal levels." (PMID 38459007, 2024). "Surprisingly, RIPA-like activity of IRF3 triggers apoptotic cell death of hepatocytes subjected to ethanol exposure, linking this activity to progression of alcoholic liver diseases." (PMID 27815826, 2017). "IRF3 was demonstrated to be critical for driving hepatocyte death in alcoholic liver disease, which also induced a strong secondary inflammatory response that affected adjacent cells by regulating NF-κB signaling, inflammatory cytokines, and apoptosis signaling, ultimately leading to liver failure." (PMID 35536585, 2022). "Besides, it is reported that interferon regulatory factor 3 (IRF3) is activated by ER stress and induce hepatocyte apoptosis in early alcoholic liver disease." (PMID 36741394, 2022).
cardiac hypertrophy (6 papers, 2015 to 2025). "In 2011, Tsushima and coworkers reported that IRF3 knockout attenuated cardiac fibrosis and ventricular chamber shrinkage in mice infused with angiotensin II, whereas cardiac hypertrophy was unaffected." (PMID 38665231, 2024).
cervical carcinoma (6 papers, 2013 to 2022). A carcinoma arising from either the exocervical squamous epithelium or the endocervical glandular epithelium. "Here, we found the direct effect of KPNA1 on cervical cancer cell proliferation, which is related to transporting IRF3 to the nucleus." (PMID 35991835, 2022). "In addition, the up-regulation of KPNA1 clearly increases the level of nuclear IRF3 and suppresses the proliferation of cervical cancer cells." (PMID 35991835, 2022). "This and our findings suggest that inhibition of kinase mediated activation or direct inhibition of IRF3 might contribute to reduction in cell’s anti-viral response and progression of cervical cancer." (PMID 26289783, 2015).
colorectal cancer (6 papers, 2014 to 2025). A primary or metastatic malignant neoplasm that affects the colon or rectum. "Our study aimed to examine potentially functional genetic variants in interferon regulatory factor 3 (IRF3), IRF5, IRF7, type I and type II IFN and their receptor genes with respect to colorectal cancer (CRC) risk and clinical outcome." (PMID 25350395, 2014).
Flavivirus Infections (6 papers, 2019 to 2025). Infections with viruses of the genus FLAVIVIRUS, family FLAVIVIRIDAE. "Most importantly, preactivation of the UPR during flavivirus infection causes a decrease of viral titers, an earlier induction of IRF3 phosphorylation and translocation, and of IFN and ISGs transcription." (PMID 31467282, 2019). "The experimental evidence presented here in the context of flavivirus infection points to a direct role of the UPR to trigger a suboptimal activation of the IRF3 pathway, which synergizes with PRR signaling to mount a potent antiviral defense." (PMID 31467282, 2019). "In particular, the critical contribution of IFN-I signal and transcription factors (IRF3, IRF5, IRF7, IPS-1, etc.)for IFN-I production to the control of in vivo flavivirus infection mostly focused on WNV has been described." (PMID 34130738, 2021). "While this, to our knowledge, has not been reported before, a non-trivial interaction and cooperation between IRF3, -7, and -5 downstream of MAVS has been observed in flavivirus infection of dendritic cells." (PMID 34685580, 2021). "Indeed, the critical role of IFN-I and its transcription factors (IRF3, IRF5, and IRF7) has been described in flavivirus infection in vivo including WNV and DenV, but not JEV." (PMID 34130738, 2021).
ischemic stroke (6 papers, 2022 to 2025). A stroke disorder caused by obstruction of blood flow to the brain, due to thrombotic (local blood clot formation) or embolic (due to a blood clot or other material traveling from another site) event. "Pharmacological inhibition of STING/IRF3 pathway attenuates neuroinflammation and confers therapeutic benefits in ischemic stroke models." (PMID 41471264, 2025). "Conversely, evidence shows that the cGAS/STING/IRF3 pathway exhibits dual roles in ischemic stroke, potentially mediating either neuroinflammatory apoptosis or functional recovery depending on activation context." (PMID 41471264, 2025). "The STING pathway has been shown to govern microglial polarization by upregulating both IRF3 and NF‐κB expression after ischemic stroke." (PMID 38372470, 2024). "Our previous work has revealed that the IRF3/NF-κB pathway is involved in the modulation of microglial polarization by STING following ischemic stroke." (PMID 39537618, 2024). "It is reported that IRF3 and NF-κB could regulate microglial polarization after ischemic stroke.We speculated that STING might influence microglial polarization through activating IRF3 and NF-κB pathways following MCAO." (PMID 35450066, 2022). "Therefore, IRF3 may exhibit functions during ischemic stroke in rats that is different from those found in mice." (PMID 35936778, 2022). "While extensively studied in ischemic stroke, the STING/IRF3 pathway’s role remains controversial, with evidence supporting both detrimental and beneficial effects." (PMID 41471264, 2025).
malaria (6 papers, 2017 to 2023). Malaria is a serious and sometimes fatal disease caused by a parasite that commonly infects a certain type of mosquito which feeds on humans. "Alike L. amazonensis, EVs from the malaria parasite were also very pro-inflammatory inducing several transcriptional factors (NF-kB and IRF3) and cytokines/chemochines via TLRs." (PMID 32850481, 2020).
non-small cell lung carcinoma (6 papers, 2013 to 2024). A group of at least three distinct histological types of lung cancer, including non-small cell squamous cell carcinoma, adenocarcinoma, and large cell carcinoma. "Beyond its antiviral function, IRF3-mediated apoptosis has been implicated in mitotic cell death of non-small cell lung carcinoma cells; consequently, IRF3 expression sensitized cells to the anti-mitotic agent Taxol." (PMID 33805458, 2021).
ovarian tumor (6 papers, 2018 to 2023). "In addition, ovarian tumor domain-containing 6B protein diminishes TRAF6-mediated K63-linked polyubiquitination of IRF3 and IRF7 to suppress IFN production." (PMID 36172355, 2022). "Previous studies have demonstrated that they play significant roles in CCHFV infection, with viral inhibition of IRF3 through the ovarian tumor (OTU) domain of the viral polymerase." (PMID 30036960, 2018). "Moreover, the ovarian tumor domain allows the OTUD1 to separate IRF3 from the promoter region of the target gene and inhibits the normal production of interferon, while it does not affect the normal dimerization of IRF3 and translocate into the nucleus." (PMID 34966378, 2021). "On the other hand, the pathway can activate IRF3 and significantly increase the expression of CCL5 and CXCL10, which leads to T cell recruitment and enhances the function of lymphocytes in ovarian tumors." (PMID 34620163, 2021).
abscess (5 papers, 2010 to 2025). An inflammatory process characterized by the accumulation of pus within a newly formed tissue cavity which is the result of a bacterial, fungal, or parasitic infection or the presence of a foreign body. "rLon treatment was shown to prevent infected Irf3−/− mice from developing severe acute kidney disease, defined by gross pathology scores (abscess formation, edema, hyperemia)." (PMID 40000737, 2025). "In Irf3−/− mice, abscesses were diffuse, destroying large tissue areas while in wt mice abscesses were morphologically distinct from surrounding healthy tissue." (PMID 20886096, 2010). "Following uropathogenic E. coli infection, Irf3−/− mice showed a pathogen-specific increase in acute mortality, bacterial burden, abscess formation and renal damage compared to wild type mice." (PMID 20886096, 2010). "In the absence of IRF3 (in the Irf3-knockout mice) the acute mortality, bacterial burden, abscess formation, and renal damage have been observed, consistent with the need for this pathway to maintain a functional antimicrobial defense." (PMID 22506110, 2012).
Acute hepatitis A (5 papers, 2020 to 2025). "As a result, CDAHFD diet increased the protein expression of IRF3 and the expression of IRF3-activated downstream proteins after 4 weeks, which is the point having hepatitis and some fibrosis." (PMID 38233853, 2024). "Acute hepatitis A caused by hepatitis A virus infection is associated with the production of chemokines such as CXCL10, which is directly activated by IRF3." (PMID 36673407, 2023). "Furthermore, IP-10 can be upregulated in an IFN-independent manner through IRF3 and RIG-I-like receptor (RLR) signaling mechanisms during Hepatitis A virus infection." (PMID 33378361, 2020).
cardiomyopathy (5 papers, 2019 to 2025). A disease of the heart muscle or myocardium proper. "We suggest that selective inhibition of IRF3 activation in non-immune cells could limit ischaemic cardiomyopathy while avoiding broad immunosuppression." (PMID 39198639, 2024).
Cerebral ischemia (5 papers, 2011 to 2025). Restriction of arterial blood supply to the brain associated with insufficient oxygenation to support the metabolic requirements of the tissue. "The cGAS/STING/IRF3 pathway mediates neuroinflammation during cerebral ischemia, where hyperactivation promotes excessive production of proinflammatory cytokines (e.g., TNF-α, IL-6) and chemokines, exacerbating cerebral damage." (PMID 41471264, 2025). "In these articles, the pretreatment using a TLR7 or TLR9 agonist reveals significant neuroprotection after cerebral ischemia by activating interferon regulatory factor 3/7- (IRF3/7)-induced type I interferon (IFN) signaling pathway." (PMID 25352781, 2014). "In another word, exposure to a minor cerebral ischemia enhances neuronal tolerance to subsequent injury and shifts cellular signaling from NF-κB pathway to IRF3, which produces IFN-b, one of the final products of IRF3 signaling pathway with neuroprotective effects." (PMID 32264928, 2020). "This is similar to TRIF deficient or IRF3 deficient mice not being protected by LPS preconditioning against cerebral ischemia." (PMID 21999375, 2011). "Interestingly, mice deficient in IRF3 are not protected against cerebral ischemia by LPS preconditioning." (PMID 21999375, 2011). "Under cerebral ischemia, ST909 activates the STING/IRF3 and IRF3/PI3K/Akt pathways to regulate microglial polarization." (PMID 41471264, 2025). "Additionally, IRF3-deficient mice could not produce a protective effect against cerebral ischemia." (PMID 25928750, 2015). "Additionally, poly-IC preconditioning can activate the expression levels of TRIF and IRF3 in the ischemic brain tissue and increase the generation of IFN-β, which further supports the protective effect of the TRIF-IRF signaling pathway in cerebral ischemia." (PMID 25928750, 2015).
glioblastoma (5 papers, 2015 to 2023). The most malignant astrocytic tumor (WHO grade IV). "Atypical EGFR signaling in glioblastoma activates the transcription factor IRF3, leading to the expression of IFI27, which often plays an important oncogenic role." (PMID 36291283, 2022). "Deregulated expression of TANK not only orchestrates the signaling network of the ERK1/2, AKT and IRF3 pathways in controlling the survival, proliferation, migration and invasion of glioblastoma (GBM) cells but also mediates the relative expression of genes in inflammatory signaling cascades." (PMID 37215097, 2023).
Glucose intolerance (5 papers, 2019 to 2024). Glucose intolerance (GI) can be defined as dysglycemia that comprises both prediabetes and diabetes. "In terms of mechanisms, deletion of IRF3 can increase the expression of PPARγ, leading to severe IR and glucose intolerance." (PMID 37303813, 2023). "As opposed to IRF3, TAZ could protect mice from HFD‐induced IR and glucose intolerance through upregulating the expression of PPARγ." (PMID 37303813, 2023).
Hyperglycemia (5 papers, 2016 to 2024). An increased concentration of glucose in the blood. "In addition, AKT pathways have been associated with the suppression of IRF3 and the reduction of inflammation in models of hyperglycemia." (PMID 35088922, 2022). "In contrast, AKT pathways are also associated with the activation of IRF3 under hyperglycemia." (PMID 35088922, 2022). "AKT pathways are believed to interact with IRF3 during hyperglycemia and influence levels of inflammatory mediators, but the exact mechanism is unclear." (PMID 35088922, 2022). "Furthermore, we revealed that the hyperglycaemia-induced cytosolic translocation of mtDNA leads to cGAS-STING-dependent IRF3/NF-kB activation, resulting in inflammation and apoptosis." (PMID 38129863, 2023). "Finally, cGAS-STING signalling was activated by hyperglycaemia-induced mtDNA release, which promoted the expression of inflammatory cytokines through the IRF3/NF-kB pathway and ultimately resulted in diabetic aortic endothelial cell dysfunction." (PMID 38129863, 2023). "Around the age of 8 months, both male and female KO mice had increased fasting glucose levels of around 180 mg/dl, and increased fasting serum insulin levels as compared with WT mice, indicating that IRF3 KO mice progressively develop hyperglycemia and hyperinsulinemia." (PMID 34091599, 2021). "Our results suggest that miR-146a decreases the levels of hyperglycemia-induced TNFα possibly through the inhibition of HMGB1, TLR4, MyD88, and TRIF/IRF3 signaling." (PMID 26997759, 2016). "Mechanistically, hyperglycaemia-induced oxidative stress promoted endothelial mitochondrial dysfunction and mtDNA release, which subsequently activated the cGAS-STING system and the cGAS-STING-dependent IRF3/NF-kB pathway, ultimately resulting in inflammation and apoptosis." (PMID 38129863, 2023).